HK2 (hexokinase 2)
Diseases named in the same sentence as HK2 in open-access papers (continued):
Sharing a sentence is not in itself a finding about the gene and the disease.
tumor (continued). "The current study found that HK2 is highly expressed in tumors, and its expression level is closely related to the malignancy of the tumor." (PMID 37234166, 2023). "Tumor cells take up glucose through glucose transporters (GLUTs) and convert it to glucose-6-phosphate(G-6-P) via hexokinase 2 (HK2)." (PMID 36778122, 2023). "LncSLCC1 can attach to AHR and actively control HK2 gene expression, inducing glycolysis activation and tumour development in CRC." (PMID 36639695, 2023). "For example, the combination of HK2 inhibitor 3-bromopyruvate and doxorubicin therapy can enhance the inhibitory effect of chemotherapy drugs on tumor growth in animal models of lung and liver cancer." (PMID 37666813, 2023). "Hexokinase is a vital enzyme in glycolysis that that contributes to the development of tumor cells by priming glucose to glucose-6-phosphate, with hexokinase 2 (HK2) being the most active isozyme." (PMID 37564659, 2023). "Depletion of HK2 in GB xenograft models decreased tumor proliferation and angiogenesis but increased tumor invasion." (PMID 37298093, 2023). "In recent years, studies have shown that HK2 in tumor cells not only mediates the Warburg effect but also inhibits tumor cell apoptosis, thereby regulating autophagy and promoting tumor proliferation." (PMID 37834257, 2023). "The enzymes of glycolysis can directly interact with the autophagy machinery (HK2) to change their activity or expression levels or to directly induce changes in autophagy in tumor cells (PFKFB4) as an adaption to cellular stress conditions." (PMID 37190124, 2023). "For example, HK2 expression is downregulated by miR‐199a‐5p and miR‐125b, and low expression of these ncRNAs corresponds to the enhancement of tumor growth." (PMID 36994237, 2023). "Many work have proven that various malignant tumors have higher expression level of HK1 and HK2, and downregulating HK2 weakens the tumor cells proliferation." (PMID 37779195, 2023). "Blocking tumor glycolysis with the HK2 inhibitor 2-DG significantly restored impaired CD8+ T cell activation." (PMID 37582735, 2023). "HK2 catalyses the first step in glucose metabolism, and HK2 is enriched in cancer cells, leading to a high glycolysis rate in tumours." (PMID 37539493, 2023). "AIMP2, a multifunctional tumor suppressor, was proposed as a potential downstream protein of HK2 by IP and mass spectrometry." (PMID 37524692, 2023). "In the tumor model, HK2 silencing led to a lower growth rate of the xenograft compared with normal HK2 expression." (PMID 37854321, 2023). "Surprisingly, HK2 has been found to be dispensable for T cell based immunity thus pitching HK2 as a putative differential target in tumor cells that heavily rely on HK2 for their energy and biosynthetic demands." (PMID 37234972, 2023). "Enhancing the connection between Akt and HK2 through K63-linked ubiquitination eventually leads to an increase in the phosphorylation of HK2 on Thr473 and mitochondrial localization, which is involved in glycolysis and tumor development." (PMID 37415097, 2023). "HK2 (increased in FLC log2 = 4.97) is required for tumor initiation and maintenance and is critical for the homeostasis of glucose in cells." (PMID 37343102, 2023). "HK2 knockdown inhibited the proliferation, migration, and invasion of DLBCL cells in vitro and restricted tumor growth in vivo, and these effects were associated with the suppression of the ERK1/2 signaling pathway." (PMID 37854321, 2023). "Tumor tissue highly expresses HK2, which acts as the first rate-limiting enzyme of the glycolytic pathway to drive growth." (PMID 37365670, 2023). "In the meantime, intense decreases in epidermal growth factor receptor activity as well as hexokinase-2 expression were detected in kaempferol-treated tumor tissue." (PMID 37239974, 2023).
tumor (continued). "In one study, exogenous histidine administration resulted in a decrease in the expression of tumor markers associated with glycolysis (GLUT1 and HK2), inflammation (STAT3), angiogenesis (VEGFB and VEGFC), and stem cells (CD133)." (PMID 37760495, 2023). "The triple combination strategy was shown to be more effective for treating HK2-positive tumours than the dual therapy of HK2-knockdown combined with OXPHOS inhibition." (PMID 37110858, 2023). "PFKFB3, together with HK2, play major roles in glycolysis that are occasionally overexpressed in aberrant tumor microenvironments (TMEs)." (PMID 38132178, 2023). "Then, HK2 acts as a protein kinase to phosphorylate IκBα and induce PD-L1 expression, leading to tumor immune escape." (PMID 37582735, 2023). "In various cancers, including CRC, HK-1 and HK-2 are upregulated to meet the high metabolic state of tumor cells and accelerate tumor cell proliferation, migration, and invasion." (PMID 37576895, 2023). "HK2 enhances the proliferation of tumor cells, inhibits cell apoptosis, and promotes cell invasion and metastasis." (PMID 36903601, 2023). "Glycolysis is mainly regulated by rate-limiting enzymes that catalyze three irreversible reactions: hexokinase (of the four HK isoenzymes, HK-2 has the most significant correlation with tumour cells), phosphofructokinase (PFK), and pyruvate kinase (PK)." (PMID 37108242, 2023). "In cancer cells, detaching HK2 from the mitochondria also induced apoptosis by releasing cytochrome c into the cytosol and deceases the tumor size." (PMID 37529037, 2023). "In GBM, HK2 binds to IκBα and phosphorylates it at Thr291, which increases PD‐L1 expression and promotes tumor immune escape." (PMID 37143582, 2023). "Of note, the ratio of CD8 + T-cell to Tregs was inversely correlated with tumor HK2 expression (spearman rho = −0.415, P = 0.012)." (PMID 36320008, 2022). "In this study, tumor cells supported energy and anabolism by upregulating HK2 and PKM2 expression to meet the metabolic requirements for abnormal proliferation." (PMID 36506561, 2022). "In summary, in CRC, poised chromatin and miR-32 decreases the expression of MARCH8, which induces HK2 degradation, represses glycolysis and acts as a tumour suppressor in CRC." (PMID 36064706, 2022). "Next, we performed real-time quantitative PCR to determine the expression of HK2 in RCC tumor and normal tissue samples." (PMID 35265223, 2022). "The combination of HK2 silencing and metformin synergistically induces cell death and suppress tumor growth." (PMID 36147929, 2022). "used a chemically-synthesized microRNA (miR-143) to inhibit glycolysis through the downregulation of hexokinase 2 (HK2), which resulted in reduction of tumor growth and corresponding decreases in FDG uptake by PET/CT." (PMID 36703796, 2022). "HK2 is required for tumor initiation in the KRAS-driven NSCLC mouse model, and the deletion of HK2 prolongs the survival of mice." (PMID 36532721, 2022). "A switch from GCK to HK2 isoenzyme occurs during the transition from primary to tumor hepatocytes so that HCC cell lines, such as Huh7, express HK2 but no longer GCK." (PMID 35055105, 2022). "Previous studies provided that overexpression of HK2 in various tumor cells can promote the transformation of glycolysis from OXPHOS to aerobic glycolysis or Warburg effect, which leads to increased glucose uptake and production of LA." (PMID 36042519, 2022). "Analysis of the Clinical Proteomic Tumor Analysis Consortium (CPTAC) database using UALCAN found that protein expression levels of HK2 were significantly increased in PAAD tissues compared with adjacent healthy tissues." (PMID 35795552, 2022). "Collectively, these data indicate that HK2 is essential for the self‐renewal and in vivo tumor propagation of liver CSCs." (PMID 35603967, 2022). "In conclusion, downregulation of lncRNA CASC7 inhibited tumour proliferation by reducing glycolysis in tumour cells through the miR-143-3p/HK2 pathway." (PMID 35474307, 2022).
tumor (continued). "IHC was used to evaluate HK2 expression in tumor cells, as an indicator of tumor glycolysis, because HK2 is the first and the rate−limiting enzyme of glycolysis." (PMID 36320008, 2022). "Overall, the results derived from human datasets and clinical samples strongly supported the possibility that UBR7 act as a tumor suppressor in HCC by regulating Keap1/Nrf2/Bach1/HK2 axis." (PMID 36419136, 2022). "HK2 is canonically thought of as the muscle-predominant hexokinase isoform, although its expression has also been found to be induced in various tumor types." (PMID 35834576, 2022). "Recently, there are several studies revealed that lncRNAs can regulate tumor metabolism and proliferation through HK2." (PMID 36072431, 2022). "Next, we found that in shCASC7 cell lines, high expression of HK2 significantly improved the proliferation of tumour cells, which is what we expected." (PMID 35474307, 2022). "Treatment of a HK2 inhibitor (3BP) conferred the recruitment of pericytes, thereby facilitating tumor vasculature remodeling and further enhancing drug delivery into tumors." (PMID 36439137, 2022). "The PVT1/miR-143/HK2 axis represents the leading target candidate for therapies to regulate cancer metabolism and block tumour progression in GBC." (PMID 34754096, 2022). "HK2 can also inhibit tumor cell apoptosis by inhibiting changes in the mitochondrial membrane’s permeability." (PMID 36555672, 2022). "CircRNF20 is a 499 bp circular RNA derived from RNF20 Gene that can promote tumor progression via miR-487a/HIF-1α/HK2 in BC." (PMID 36532768, 2022). "Some tumor tissues from nude mice were randomly selected in each group, and the expression of HK2, PKM2, and LDHA proteins in tumor tissues was detected by Western blotting." (PMID 36467556, 2022). "Genistein directly downregulated protein expression of HIF-1 in HCC cells, consequently inactivated GLUT1 and HK2 to impede aerobic glycolysis and accelerated tumor cell death." (PMID 36339566, 2022). "For example, hexokinase 2 is a crucial enzyme that aids the progression and resistance of cancer cells by promoting tumor glycolysis." (PMID 35326612, 2022). "Under these circumstances, HK2 plays a key role in tumor initiation and development as the first enzyme in the glycolysis pathway that phosphorylates glucose to G6P, introducing glucose into pathways required for anabolic activities in cancer cells." (PMID 35269760, 2022). "Hexokinase 2 (HK2) plays a critical role in regulating aerobic glycolysis in tumor cells and has become one of the main targets of tumor therapy." (PMID 36212414, 2022). "New evidence has revealed that reduced mtDNA promotes tumor survival by operating in favor of aerobic glycolysis, which is accompanied by increases in HK2 and phosphofructokinase (PFK) activities, glucose uptake, and lactic acid." (PMID 36359776, 2022). "The mitochondrial localization of HK2 can play an important role in the metabolic remodeling of tumor cells, and HK2 in mitochondria is closely related to the production of ATP, which contributes to the combination of glycolysis and oxidative phosphorylation." (PMID 36555672, 2022). "As the critical rate-limiting enzymes of glycolysis, HK2 catalyzes the first irreversible step of glycolysis, which increases at significantly elevated levels in a variety of tumor cells." (PMID 35431949, 2022). "HK2 promotes tumor growth by maintaining a high glycolysis rate in fast-growing tumors, and the microRNA (miR)-216a-5p/HK2 axis plays a significant role in UM tumorigenesis." (PMID 36003786, 2022). "Previously, we evaluated tumor HK2 expression, as a marker of glycolysis and analyzed the relationship between tumor HK2 expression and T cell function/infiltration." (PMID 36320008, 2022). "For instance, erastin and Ras-selective lethal small molecule 3 (RSL3) results in tumour cells ferroptosis and a decrease in activities of the key rate-limiting enzymes (HK2 and PKM2) in glycolysis." (PMID 36578477, 2022).
tumor (continued). "High expression of HK2 in tumor tissues is critical for the proliferation, migration, and chemoresistance of tumor cells." (PMID 36172793, 2022). "HK2 is abnormally expressed in high amounts in many cancers, which is very important for tumor initiation, and maintenance and is closely related to cancer treatment and prognosis." (PMID 36059961, 2022). "HK2 has been reported to be required for tumor initiation in mouse models and is related to cancer cell proliferation and metastasis in neuroblastoma and gallbladder cancer." (PMID 36115986, 2022). "Above, we have established that HK2 overexpression is positively correlated with the tumor stage, differentiation, and lymph node metastasis, thereby associated with the development of RCC." (PMID 35265223, 2022). "The results of IHC staining and Western blotting indicated that 200 mg/kg NaBu inhibited the expression of HK2 in the mouse tumour tissues." (PMID 35429101, 2022). "In summary, we propose that in CRC, poised chromatin and miR-32 decrease the expression of MARCH8, further bind and add ubiquitin, induce HK2 degradation, and finally repress glycolysis to promote tumor suppressors in CRC." (PMID 36064706, 2022). "It is well known that the biological effects of miRNAs are achieved by regulating mRNA level, so we used bioinformatics websites to predict the potential target gene of miR-653, HK2 was selected as the target of miR-653 because of its tumor-promoting impact." (PMID 35379058, 2022). "Next, we utilized the KIRC cohort of TCGA and GTEx data to analyze the differential expression of HK2 in tumor and normal tissue samples." (PMID 35265223, 2022). "Studies have shown that HIF-1α activation can upregulate the levels of HK1 and HK2 and that it plays an important role in tumor cell proliferation by enhancing glycolysis activity." (PMID 35957825, 2022). "Together, these findings suggest that tumor HK2 expression influences patient survival indirectly via distinct immune profiling, specifically a low ratio of CD8 + T-cells to Tregs." (PMID 36320008, 2022). "HK2 has high expression levels in many types of human tumor, together with increased expressions of phosphofructokinase (PFK), other glycolytic enzymes, and glucose-6-phosphate dehydrogenase (G6PD)." (PMID 35216280, 2022). "KIAA1429 is not only potentially related to immunity but is also an upstream gene of the key glycolytic enzyme HK2, which enhances the stability of HK2 in an m6A‐dependent manner, thereby promoting tumor glycolysis." (PMID 38089085, 2022). "In this paper, we first reported the relationship between HK2 gene alteration and the survival prognosis of different tumor types." (PMID 36335239, 2022). "Whereas HK2 knockdown synergistically inhibited tumor growth with sorafenib, suggesting that HK2 inhibition significantly improves the efficacy of sorafenib." (PMID 36071839, 2022). "A concentration of 200 mg/kg NaBu lowered the lactate levels and the expression of HK2 in the mouse tumour tissues." (PMID 35429101, 2022). "Blocking glycolysis activity via HK2 inhibition also suppressed the vascular network formation and extravasation of tumor cells." (PMID 35158779, 2022). "We used the GEPIA2 tool to combine all tumor expression data of TCGA and obtained the top 100 genes that related to HK2 expression." (PMID 36335239, 2022). "The high level of HK2 expression and activity in glycolytic tumor cells has been revealed in PET imaging." (PMID 35805008, 2022). "Systemic HK2 deletion increased the time required to reach endpoint (when a tumor reached ~2 cm in diameter)." (PMID 35173161, 2022). "HK2 is usually expressed in skeletal, cardiac muscle and adipose tissues, as well as many malignant tumour tissues." (PMID 35982398, 2022). "HK2 acts as the first rate-limiting enzyme of glycolysis and also helps tumor cells escape apoptosis by localizing itself on the outer membrane of the mitochondria." (PMID 36555672, 2022).
tumor (continued). "NQO1 was overexpressed in NSCLC, and the knockdown of the NQO1 gene expression by its specific siRNA inhibited cell proliferation and tumor glycolysis metabolism in A549 cells by downregulating HK2 expression." (PMID 36532721, 2022). "The paraffin sections of tumor tissues of nude mice were stained with IHC to detect the expression of HK2, PKM2, and LDHA, the key enzymes of aerobic glycolysis." (PMID 36467556, 2022). "A previous study has discovered that miR-143 controls tumor cell glycolysis by influencing HK2, a key glycolytic pathway enzyme." (PMID 36483029, 2022). "This is consistent with the well-documented role of AKT in the regulation of mitochondrial hexokinases and the reports that enhanced HK2 activity is an important mechanism for tumor survival." (PMID 35953818, 2022). "Further analysis revealed that high lncRNA CASC7 expression in tumours seemed to correspond to high expression of HK2, and this phenomenon was verified by immunohistochemical analysis." (PMID 35474307, 2022). "The Cu-PS, a 5-genes (C7, MAGEA6, HK2, CYP26B1 and EPO) signature, was significantly associated with TNM stage, tumor mutational burden (TMB), drugs sensitivity, and immunotherapies response." (PMID 36250008, 2022). "A previous study showed that HK2 inhibitor 3-bromopyruvic acid (3-BP) significantly inhibits the progression and proliferation of tumor cells in HK2- expressing colorectal cancer." (PMID 36212414, 2022). "For instance, Honokiol (HNK), a natural compound, inhibited the glycolysis of BC cells and indirectly blocked tumor growth by targeting HIF-1α/GLUT1/PDK1/HK2 pathway." (PMID 36532768, 2022). "Regarding a possible treatment, we showed that ectopic expression of IL13Rα1 plus HK2 inhibition additively inhibited tumor growth under castration resistance conditions." (PMID 34652890, 2021). "Another report indicated that HK2 promotes the proliferation of CC cells in vitro and tumor formation in vivo by regulating the Raf/MEK/ERK signaling pathway." (PMID 34858863, 2021). "Disrupting these functions by targeting HK2 subcellular localization can constitute a promising anti-tumor strategy." (PMID 33946854, 2021). "Enhancement of glucose transporter-2 on the cell membrane and glycolytic enzymes, such as hexokinase-2, usually means the presence of an aggressive tumor that is growing rapidly." (PMID 34203396, 2021). "By mediating Akt ubiquitination, TRAF6 promoted Akt activation and enhanced HIF-1 mediated transcription of hexokinase-2, giving rise to the increase of tumor glycolysis in NSCLC." (PMID 34409101, 2021). "In many tumor cells, HK2 displacement from MAMs rapidly elicits a massive Ca2+ flux to mitochondria that leads to mPTP opening and apoptosis and can be blocked by IP3R inhibition." (PMID 33946854, 2021). "These molecules target HK2 in many in vitro and in vivo tumor models, detach it from mitochondria and elicit tumor cell death." (PMID 33946854, 2021). "MiR-206 is also a tumor-suppressive miRNA by modulating the HK2 expression by binding on the 3′-UTR of HK2." (PMID 33916349, 2021). "Several studies 30-35 confirmed that HK2 expression is increased in various tumor tissues and is closely related to the progression of malignant tumors." (PMID 34234853, 2021). "The expression of HK2 in tumor grade 3 was lower than that in tumor grade 2 (P < 0.01) and 1 (P < 0.05), respectively." (PMID 34708035, 2021). "The in vivo data indicated that upregulation of HK2 significantly delivered lncSLCC1 downregulation induced decline in the tumor growth and tumor weight." (PMID 33602893, 2021). "Since HK2 is a key mediator of glycolysis, its inhibitor, 3-bromopyruvate, has been extensively tested as a single anticancer agent for treating preclinical tumor models." (PMID 34650057, 2021).